CYP27A1 (cytochrome P450 family 27 subfamily A member 1)
Description:
Cytochrome P450 monooxygenase that catalyzes regio- and stereospecific hydroxylation of cholesterol and its derivatives. Hydroxylates (with R stereochemistry) the terminal methyl group of cholesterol side-chain in a three step reaction to yield at first a C26 alcohol, then a C26 aldehyde and finally a C26 acid. Regulates cholesterol homeostasis by catalyzing the conversion of excess cholesterol to bile acids via both the 'neutral' (classic) and the 'acid' (alternative) pathways. May also regulate cholesterol homeostasis via generation of active oxysterols, which act as ligands for NR1H2 and NR1H3 nuclear receptors, modulating the transcription of genes involved in lipid metabolism. Catalyzes the conversion of 7-ketocholesterol (7-oxocholesterol) into 7-keto,27-hydroxycholesterol, a precursor of 7-keto,27-hydroxycholesterol, an active oxysterol that activates smoothened (SMO) and the smoothened signaling pathway (By similarity). Plays a role in cholestanol metabolism in the cerebellum. Similarly to cholesterol, hydroxylates cholestanol and may facilitate sterol diffusion through the blood-brain barrier to the systemic circulation for further degradation. Also hydroxylates retinal 7-ketocholesterol, a noxious oxysterol with pro-inflammatory and pro-apoptotic effects, and may play a role in its elimination from the retinal pigment epithelium. May play a redundant role in vitamin D biosynthesis. Catalyzes 25-hydroxylation of vitamin D3 that is required for its conversion to a functionally active form.
Synonyms: CYP27; CTX; CP27
Tractability: Small molecule: it belongs to a druggable protein family. Antibody: UniProt places it where antibodies can reach, with medium confidence. PROTAC: its protein half-life has been measured; a small molecule that binds it is known.
Target class: Cytochrome P450 family 27A; Cytochrome P450; Cytochrome P450 family 27; Cytochrome P450 27A1; Enzyme
Gene: Protein-coding gene on chromosome 2 (218,781,738 to 218,815,293, forward strand). Ensembl gene ENSG00000135929.
Subcellular location: Mitochondrion inner membrane
Subcellular location (Human Protein Atlas): Mitochondria; Cytosol
Pathways (Reactome):
Metabolism: Endogenous sterols; Synthesis of bile acids and bile salts via 24-hydroxycholesterol; Synthesis of bile acids and bile salts via 27-hydroxycholesterol; Synthesis of bile acids and bile salts via 7alpha-hydroxycholesterol
Disease: Defective CYP27A1 causes CTX
Gene Ontology:
Molecular function: cholestanetetraol 26-dehydrogenase activity; cholesterol 26-hydroxylase activity; heme binding; oxidoreductase activity, acting on paired donors, with incorporation or reduction of molecular oxygen, another compound as one donor, and incorporation of one atom of oxygen; vitamin D3 25-hydroxylase activity; steroid hydroxylase activity; iron ion binding; monooxygenase activity; oxidoreductase activity, acting on paired donors, with incorporation or reduction of molecular oxygen
Biological process: bile acid biosynthetic process; calcitriol biosynthetic process from calciol; cholesterol catabolic process; cholesterol metabolic process; positive regulation of smoothened signaling pathway; sterol metabolic process; lipid biosynthetic process; steroid metabolic process
Cellular component: mitochondrion; mitochondrial inner membrane; mitochondrial matrix
Genetic constraint (gnomAD): Loss-of-function variants: 53 observed, 64.11 expected, observed/expected ratio (o/e) 0.83, 90% interval 0.66 to 1.04. The upper end of that interval is the gene's LOEUF score, 1.04, which puts it in group 4 of 6, group 1 being the genes least tolerant of losing a copy. Missense variants: 704 observed, 711.74 expected, observed/expected ratio (o/e) 0.99, 90% interval 0.93 to 1.05. Synonymous variants: 274 observed, 295.72 expected, observed/expected ratio (o/e) 0.93, 90% interval 0.84 to 1.02.
Gene-disease validity (ClinGen):
ClinGen rates the evidence that CYP27A1 causes each of these diseases.
cerebrotendinous xanthomatosis (autosomal recessive): Definitive. Cerebrotendinous xanthomatosis (CTX) is an anomaly of bile acid synthesis characterized by neonatal cholestasis, childhood-onset cataract, adolescent to young adult-onset tendon xanthomata, and brain xanthomata with adult-onset neurologic dysfunction.
Homologues: Orthologues: chimpanzee CYP27A1 (99% identical), macaque CYP27A1 (96% identical), dog CYP27A1 (80% identical), pig CYP27A1 (78% identical), guinea pig CYP27A1 (78% identical), rat Cyp27a1 (73% identical), mouse Cyp27a1 (72% identical), rabbit CYP27A1 (69% identical), tropical clawed frog cyp27a1.2 (49% identical), tropical clawed frog cyp27a1 (48% identical), tropical clawed frog cyp27a1.3 (47% identical), zebrafish cyp27a1.2 (44% identical), and 4 more. Paralogues in human: CYP27B1 (37% identical), CYP27C1 (35% identical), CYP24A1 (29% identical).
Diseases named in the same sentence as CYP27A1 in open-access papers:
CYP27A1 is named in the same sentence as 196 diseases in open-access papers, as found by Europe PMC text mining. Sharing a sentence is not in itself a finding about the gene and the disease. The quoted sentences say what the papers report.
cerebrotendinous xanthomatosis (115 papers, 2010 to 2026). "Cerebrotendinous Xanthomatosis (CTX) is a rare genetic disorder due to variants in the CYP27A1 gene, inherited in an autosomal recessive manner." (PMID 39967585, 2025). "Cerebrotendinous xanthomatosis (CTX), also known as cerebral cholesterinosis, is a rare, autosomal recessive, lipid storage disorder caused by mutations in the CYP27A1 gene." (PMID 41324091, 2025). "Cerebrotendinous xanthomatosis (CTX) is caused by mutations in the CYP27A1 gene, which encodes for sterol 27‐hydroxylase." (PMID 40464291, 2025). "Cerebrotendinous xanthomatosis (CTX) is a rare autosomal recessive lipid storage disorder caused by pathogenic variants in the CYP27A1 gene, which encodes sterol 27-hydroxylase, an enzyme in the cytochrome P450 oxidase family." (PMID 39595922, 2024). "Cerebrotendinous Xanthomatosis (CTX) is a rare autosomal recessive lipid storage disorder caused by loss of function variants in the CYP27A1 gene which encodes sterol 27-hydroxylase, on chromosome 2q35." (PMID 38336741, 2024). "Cerebrotendinous xanthomatosis (CTX) is a rare metabolic disorder caused by mutations in the CYP27A1 gene, leading to cholestanol accumulation in various tissues, including peripheral nerves." (PMID 39595922, 2024). "A splice site mutation in CYP27A1 has been reported to lead to cerebrotendinous xanthomatosis which can be characterized by pulverulent cataracts and gastrointestinal problems such as diarrhea." (PMID 38984127, 2024). "Cerebrotendinous xanthomatosis (CTX) is an autosomal recessive genetic disease caused by mutations in the CYP27A1 gene and is characterized by the deposition of cholestanol in the brain, tendons, eye lenses, and other organs." (PMID 37937646, 2023). "Second, CYP27A1 deficiency in humans leads to cerebrotendinous xanthomatosis, a lipid storage disorder, which has ocular manifestations, including those in the retina." (PMID 36914277, 2023). "Cerebrotendinous xanthomatosis (CTX) is a genetic lipid storage disease caused by a mutation in the sterol 27-hydroxylase (CYP27A1) gene." (PMID 37960277, 2023). "Cerebrotendinous Xanthomatosis represents a rare and underdiagnosed inherited neurometabolic disorder due to homozygous or compound heterozygous variants involving the CYP27A1 gene." (PMID 36619921, 2022). "For example, rs41272687, for which we report a novel association with circulating metabolites (p = 8.72 × 10−14 with 7-HOCA), is a missense mutation in the CYP27A1 gene, whose mutations cause cerebrotendinous xanthomatosis." (PMID 35050183, 2022). "Cerebrotendinous xanthomatosis (CTX) is a rare autosomal recessive disorder caused by sterol 27-hydroxylase deficiency (encoded by CYP27A1), leading to a decreased synthesis of bile acids with consecutive abnormal production of cholestanol." (PMID 36514115, 2022). "Cerebrotendinous xanthomatosis (CTX) is a rare genetic disorder related to CYP27A1 biallelic mutations, leading to decreased synthesis of bile acids and increased cholestanol." (PMID 36514115, 2022). "A 63-year-old woman with progressive cognitive decline, pyramidal signs, and bilateral cataract was treated by chenodeoxycholic acid following the diagnosis of cerebrotendinous xanthomatosis due to a homozygous variant in CYP27A1." (PMID 34066437, 2021). "Homozygous or compound heterozygous mutations in CYP27A1 lead to cerebrotendinous xanthomatosis (CTX), a lipid storage disorder associated with a diverse range of neurological dysfunctions." (PMID 33802612, 2021). "Cerebrotendinous xanthomatosis (CTX) is a disorder of bile acid synthesis caused by mutations in the cytochrome P450 CYP27A1 gene." (PMID 34121999, 2021). "Cerebrotendinous xanthomatosis is a rare autosomal recessive lipid storage disease caused by a defect in CYP27A1 gene, encoding the mitochondrial cytochrome P450 sterol 27-hydroxylase enzyme." (PMID 33400472, 2021).
cerebrotendinous xanthomatosis (continued). "Cerebrotendinous xanthomatosis (CTX) is a rare autosomal recessive lipid deposition disorder caused by a sterol 27-hydroxylase (CYP27A1) gene mutation." (PMID 33655933, 2021). "A unique family affected by cerebrotendinous xanthomatosis due to autosomal recessive mutations in CYP27A1 presented with asymmetric parkinsonism, apraxia, and dystonia, resembling a CBS phenotype." (PMID 33467748, 2021). "Patient 31 was considered to have Cerebrotendinous Xanthomatosis (CTX) caused by a CYP27A1 mutation, which has been associated with infantile cholestasis in several studies, and it can present as a benign course or severe course." (PMID 33763395, 2021). "In the peripheral nerve system, polyneuropathy is a clinical manifestation in cerebrotendinous xanthomatosis, which is a rare autosomal recessive disorder of bile-acid metabolism caused by deficiency of the sterol 27-hydroxylase (Cyp27a1) gene." (PMID 33947104, 2021). "Another HSP related to defective cholesterol hydroxylation is cerebrotendinous xanthomatosis (CTX) due to CYP27A1 mutations, which encodes the mitochondrial cytochrome P450 enzyme sterol 27-hydroxylase." (PMID 32180696, 2020). "Cerebrotendinous xanthomatosis (CTX) is a rare autosomal recessive bile acid disorder caused by the deficiency of the mitochondrial enzyme 27-sterol hydroxylase (CYP27A1)." (PMID 32714376, 2020). "Two genes, Gja1 and Cyp27a1 have a striking monogenic association with oculodentodigital dysplasia and cerebrotendinous xanthomatosis respectively, both of which are associated with retinal abnormalities." (PMID 29116131, 2017). "Cerebrotendinous xanthomatosis (CTX) is a very rare autosomal recessive disorder caused by mutations in the CYP27A1 gene (Björkhem and Hansson, 2010; Bjorkhem, 2013)." (PMID 27920719, 2016). "Mutations in CYP27A1 cause cerebrotendinous xanthomatosis, a rare autosomal recessive lipid storage disease." (PMID 27367670, 2016). "CYP27A1 is a key enzyme in the alternative bile acid synthesis pathway, and mutations in this enzyme can cause cerebrotendinous xanthomatosis." (PMID 27920719, 2016). "And it is known that mutations in CYP27A1 are associated with cerebrotendinous xanthomatosis, a rare lipid storage disease with the deposition of a form of cholesterol (cholestanol) in the brain and other tissues." (PMID 25628655, 2015). "Cerebrotendinous xanthomatosis (CTX) OMIM#213700 is a rare autosomal-recessive lipid storage disease caused by mutations in the CYP27A1 gene; this gene codes for the mitochondrial enzyme sterol 27-hydroxylase, which is involved in bile acid synthesis." (PMID 25424010, 2014). "Cerebrotendinous Xanthomatosis (CTX) is a rare autosomal recessive sterol storage disease caused by a mutated sterol 27-hydroxylase gene (CYP27A1)." (PMID 22018287, 2011). "Cerebrotendinous xanthomatosis is caused by a mutation in a gene called CYP27A1, which produces the enzyme, sterol 27-hydroxylase." (PMID 21369420, 2010). "CYP27A1 alterations are associated with cerebrotendinous xanthomatosis (MIM #213700)." (PMID 40208338, 2025). "Therefore, patients with a CYP27A1 deficiency develop cerebrotendinous xanthomatosis (CTX), which is a devastating neurological milieu, due to the accumulation of cholesterol and 5α-cholestanol in the brain and tendons." (PMID 37408268, 2023). "In humans, Cyp27a1 deficiency leads to cerebrotendinous xanthomatosis (CTX)." (PMID 34512255, 2021). "Moreover, in one case, a homozygous variant in the CYP27A1 gene, known as pathogenic in cerebrotendinous xanthomatosis (CTX), was identified." (PMID 30778698, 2019).
cerebrotendinous xanthomatosis (continued). "Background and Clinical Significance: Cerebrotendinous xanthomatosis (CTX) is a rare autosomal recessive disorder caused by mutations in the CYP27A1 gene, leading to impaired bile acid synthesis and systemic cholesterol deposition." (PMID 40710868, 2025). "Cerebrotendinous xanthomatosis (CTX) is a rare autosomal recessive disorder caused by mutations in the CYP27A1 gene, leading to deficient sterol 27‐hydroxylase activity." (PMID 41324091, 2025). "Cerebrotendinous xanthomatosis (CTX) is an autosomal recessive lipid metabolism disorder caused by a defect in the sterol-27-hydroxylase gene (CYP27A1) on chromosome 2." (PMID 38669366, 2024). "Although mutations in CYP27A1 lead to cerebrotendinous xanthomatosis (CTX), a disease characterized by cholesterol accumulation and premature atherosclerosis, the regulatory role of CYP27A1 remains uncertain." (PMID 39062040, 2024). "Cerebrotendinous xanthomatosis (CTX) is a disease that affects bile acid synthesis and is caused by an autosomal recessive mutation in CYP27A1." (PMID 38673463, 2024). "Cerebrotendinous Xanthomatosis (CTX) is a treatable disorder of bile acid synthesis caused by deficiency of 27-sterol hydroxylase -encoded by CYP27A1- leading to gastrointestinal and progressive neuropsychiatric symptoms." (PMID 36529270, 2023). "The “free” testing is an effort to diagnose children with Cerebrotendinous xanthomatosis (CTX), a rare cause of syndromic cataracts due to lipid storage secondary to pathogenic variants in CYP27A1 gene." (PMID 36981008, 2023). "Cerebrotendinous xanthomatosis (CTX) is a genetic disorder of the cholesterol metabolic pathway, most often associated with variants in the CYP27A1 gene." (PMID 37239101, 2023). "Cerebrotendinous xanthomatosis (CTX), also known as CTX, is an extremely rare bile acid metabolic disorder caused by mutations in the cytochrome P450 family 27 subfamily A member 1 (CYP27A1) gene." (PMID 36628393, 2023). "Homozygous or compound heterozygous mutations in the CYP27A1 gene (located on chromosome 2q35) cause cerebrotendinous xanthomatosis (CTX) (OMIM, 213,700), a rare autosomal recessive lipid storage disease." (PMID 35743896, 2022). "Among them, cerebrotendinous xanthomatosis (CTX) is caused by mutations in the CYP27A1 gene resulting in the impairment of sterol 27-hydroxylase enzyme activity." (PMID 33520900, 2021). "Humans with a loss of function mutation in the CYP27A1 gene suffer from Cerebrotendinous xanthomatosis (CTX)." (PMID 33193099, 2020). "Cerebrotendinous xanthomatosis (CTX) is an autosomal recessive disorder of bile acid synthesis caused by mutations in the CYP27A1 gene." (PMID 32714376, 2020). "Cerebrotendinous xanthomatosis (CTX) is a rare inborn lipid-storage disease caused by mutations in the sterol 27-hydroxylase (CYP27A1) gene with an autosomal recessive pattern of inheritance." (PMID 31796091, 2019). "Pathogenic variants in the cytochrome P450 CYP27A1 gene result in the production of a defective sterol 27-hydrolase enzyme and have been linked with cerebrotendinous xanthomatosis (CTX) (OMIM #213700)." (PMID 30778698, 2019). "The human autosomal recessive disease, cerebrotendinous xanthomatosis (CTX), results from a deficiency in cytochrome P450 27A1 (CYP27A1), a key enzyme in the conversion of cholesterol to bile acids." (PMID 30736477, 2019). "In human, mutations in the CYP27A1 gene are the cause of the autosomal recessive disease cerebrotendinous xanthomatosis (CTX)." (PMID 30471425, 2019). "The patient was diagnosed with cerebrotendinous xanthomatosis (CTX) based on an elevated serum cholestanol level and a homozygous missense mutation in CYP27A1." (PMID 30891321, 2019). "Cerebrotendinous xanthomatosis (CTX) is a rare autosomal recessive disease caused by a deficiency in sterol 27-hydroxylase (CYP27A1), a key enzyme in the synthesis of chenodeoxycholic acid (CDCA), a primary bile acid." (PMID 26861945, 2016).